IDO1 (indoleamine 2,3-dioxygenase 1)
Diseases named in the same sentence as IDO1 in open-access papers (continued):
Sharing a sentence is not in itself a finding about the gene and the disease.
tumor (continued). "In human tumors, IDO1 expression usually correlates with a poor prognosis and is linked to a more aggressive tumor phenotype, a reduced tumor infiltrate, and an increased number of regulatory T-cells at the tumor site." (PMID 25691885, 2015). "IDO1 activation is associated with the generation of a regulatory phenotype in T cells and dendritic cells, and is involved in tumor immune escape." (PMID 26236243, 2015). "In contrast, IDO1 deficiency was shown to decrease Treg recruitment and to enhance T-cell-mediated tumor rejection." (PMID 26378585, 2015). "IDO-1 has been shown to protect tumors from an attack by tumor-associated, antigen-specific host cytotoxic T cells." (PMID 25928531, 2014). "Reversal of tumor-associated immune suppression by 1-d-MT appears to be dependent on host IDO1 expression in preclinical models." (PMID 25628622, 2014). "Ido1 inhibition in 4T1 tumor cells was associated with significant changes in the expression of 40 cell cycle genes involved in the G1/S transition, S phase, G2/M transition, checkpoints, and M phase, and the majority of the altered genes were downregulated." (PMID 22654951, 2012). "Vascular endothelial cells (EC) have been implicated in expression of IDO1 and tryptophan-degrading activity in the context of infectious diseases, tumour pathology and transplantation." (PMID 21755000, 2011). "Additionally, its existence reduced GBM cell proliferation, but the tumor promotion effect of IDO1 was caused by the pro-cancer ability to resist the cell death program surpassing the effect of cell proliferation inhibition." (PMID 39863603, 2025). "Tumor cells and immunosuppressive cells (e.g., tumor-associated macrophages (TAMs) and myeloid-derived suppressor cells (MDSCs)) express enzymes like arginase 1 (Arg-1) and indoleamine 2,3 dioxygenase (IDO1), depleting arginine and tryptophan in the TME." (PMID 40944200, 2025). "Conversely, the immunosuppressive activity of Tregs has been linked to tumor-mediated upregulation of enzymes such as indoleamine 2,3-dioxygenase 1 (IDO1), which may further contribute to immune evasion." (PMID 40867165, 2025). "Moreover, tumor-associated IDO1 overexpression serves as an independent predictor of disease recurrence and distant metastasis." (PMID 41208974, 2025). "Additionally, PTEN-deficient tumours show increased expression of immune evasion markers, including programmed death-ligand 1 (PD-L1) and indoleamine 2,3-dioxygenase 1 (IDO1), which damage the cytotoxic activity of immune cells and facilitate immune escape." (PMID 40165885, 2025). "Furthermore, research on the tryptophan–kynurenine pathway, mediated by the enzyme IDO1, has revealed serotonin depletion and the accumulation of neurotoxic metabolites as possible mediators of tumor-associated depression." (PMID 41514529, 2025). "Therefore, the activity of IDO1 is associated with immune responses, chronic inflammation, tumor immune escape, and various other pathological processes." (PMID 39940736, 2025). "Tumor cells, tumor-associated macrophages, and certain dendritic cells can decrease local tryptophan levels by provoking metabolic enzymes, including indoleamine 2,3-dioxygenase (IDO1) and tryptophan 2,3-dioxygenase (TDO2)." (PMID 41179661, 2025). "In line with previous observations, the data in the current manuscript delve into the molecular mechanisms by which IDO1 inhibitors could cause an adverse tumor-protective effect." (PMID 41262240, 2025). "Notably, within the tumor microenvironment, IDO1 facilitates the polarization of tumor-associated macrophages (TAMs) towards the immunosuppressive M2 phenotype through a metabolic cascade mechanism." (PMID 40370742, 2025). "High levels of IDO1 in tumours inhibit anti-tumour T cells and is associated with poor prognosis." (PMID 40430784, 2025).
tumor (continued). "For instance, IDO1 produced in APCs might increase peripheral tolerance to tumor-associated antigens (TAAs) in tumor-draining lymph nodes, maintaining the activity of TAA-expressing malignant cells." (PMID 41035912, 2025). "IDO1 expression is often associated with tumor immune escape." (PMID 40062505, 2025). "Additionally, IDO1/TDO expression has been linked to tumor malignancy, with patients exhibiting positive IDO1/TDO protein expression having shorter survival times." (PMID 40075568, 2025). "IDO1 is strongly implicated in tumor immune tolerance and immune escape." (PMID 40332338, 2025). "Single-cell RNA analysis of CRC patient samples revealed that the presence of highly expressing IDO1 macrophages, in comparison to low-IDO1 expressing macrophages, was associated with higher immune cell infiltration, higher immune checkpoint expression, and lower tumor progression." (PMID 40361394, 2025). "IDO1 has been extensively studied in the context of cancer, where its overexpression is often linked to immune evasion by tumor cells, potentially through mechanisms such as inhibiting T cell activation, promoting T cell apoptosis, and expanding regulatory T cell (Treg) populations." (PMID 40715082, 2025). "This provides a reference for studying IDO1‐related angiogenesis in the tumor context, and exploring its underlying mechanisms could offer a basis for new drug development or more rational and effective combination therapies." (PMID 40103267, 2025). "In some cases, high expression of IDO1 might be associated with immune evasion and tumor progression, whereas in other scenarios, it could be linked to immune activation and antitumor responses." (PMID 40217479, 2025). "This suggests that IDO1 may be an important regulatory protein that causes tumor immunosuppression and plays an important role in tumor progression and recurrence." (PMID 38254043, 2024). "IFN-γ-induced IDO1 expression causes tryptophan starvation and kynurenine accumulation, which could have an extensive impact on tumor environment immune cells." (PMID 38540186, 2024). "Interestingly, although IDO1 expression is commonly associated with immunosuppression and tumor invasion, IDO1 is associated with improved therapeutic response in NSCLC treated with PD‐L1 blockade, which is not observed in conventional chemotherapy." (PMID 38469550, 2024). "Whether intra-tumor NAD+ depletion through IDO1 inhibitors might be an additional mechanism underlying the antitumor activity of these agents remains to be defined." (PMID 38396769, 2024). "One of the two altered-excluded tumors displayed IDO1 expression in 60% of tumor cells, which could have caused or at least contributed to immune cell exclusion from the main tumor area." (PMID 39061522, 2024). "IDO1 has been shown to be highly expressed in tumor cells of various cancers, suggesting that the depletion of tryptophan associated with increased IDO1 activity plays a vital role in suppressing tumor immunity." (PMID 38234210, 2024). "Herein, we further investigated the association between glycolysis and IDO1 in PC with bioinformatic analysis and found the expression of SLC2A1, SLC2A3, SLC2A5 (encoding GLUT1, GLUT3, GLUT5 protein), and IDO1 in the tumor tissues of PC patients was increased compared to the adjacent normal tissues." (PMID 38706741, 2024). "In addition to suppressing immune responses, IDO1 can potentially contribute to tumor progression by enhancing the rate of angiogenesis by causing the proliferation of CD105-expressing human umbilical vein endothelial cells." (PMID 39371092, 2024). "We next investigated whether the increased IDO1 observed in Dock2 deficient tumours impacted on tryptophan metabolism." (PMID 39242821, 2024). "Furthermore, IDO1 expression was connected to the tumour mutational burden, microsatellite instability, mismatch repair, drug sensitivity, immune cells infiltrating, and the tumour immune microenvironment across various cancer types." (PMID 39064305, 2024).
tumor (continued). "This defective recognition of cancer cells together with the upregulation of IFNγ in DOCK-2 deficient T cells may result in tumour promotion via increased expression of IDO1." (PMID 39242821, 2024). "Our findings are consistent with the previous studies and suggested that IDO1 over-expressed in tumor cells associated with Trp-kyn metabolic reprogramming could increase secretion of L-kyn enriched EVs." (PMID 38468343, 2024). "Interferon-gamma is closely associated with IDO1 expression in tumor treatment and prognosis." (PMID 38539263, 2024). "IDO1 is overexpressed in various tumor types and associated with worse overall survival." (PMID 38706595, 2024). "In addition, we previously reported that MCC cases with low indoleamine 2,3-dioxygenase 1 expression in tumor cells and low tryptophan 2,3-dioxygenase 2 and aryl hydrocarbon receptor expression in tumor stroma are associated with good prognosis." (PMID 37573372, 2023). "Another study reported that HGSOC tumours with a high level of IDO1 might be resistant to therapy and were associated with significantly lower overall survival and progression‐free survival." (PMID 38062922, 2023). "IDO1 inhibitors may restore anti-tumor immunity, which is blocked by a tryptophan-deficient milieu resulting from IDO1+ myeloid cells and IDO1 expressing tumor cells." (PMID 37196768, 2023). "CD8+ T lymphocytes may release IFNγ to upregulate PD-1/PD-L1 and IDO1 gene expression, with IDO1 overexpression linked to poor prognosis, tumour development, and metastasis." (PMID 37760841, 2023). "IDO1 regulates the tryptophan-kynurenine (Kyn) pathway in advanced cancers, including mRCC, and thus appears as a key enzyme associated with immunomodulation and tumor immune evasion." (PMID 37370768, 2023). "ECI2, PPT2, ACSM3, PMVK, and IDO1 were low expressed in the prognosis of high-risk patients, which may be tumor suppressor factors." (PMID 37256178, 2023). "In this model system, genetic loss of IDO1 caused a substantial delay in tumor outgrowth." (PMID 37182174, 2023). "Taken together, these data suggest that high SRC-3 causes EMT, leading to the recruitment of Tregs into the tumor microenvironment and to an increase in IDO-1 expression, thereby contributing to the development of an immunosuppressive microenvironment and thereby to failure of immunotherapy in BCa." (PMID 37958417, 2023). "Overexpression of IDO1 in tumor cells has been associated with a poor prognosis." (PMID 38275827, 2023). "We next asked whether the IDO1-induced TRP loss in fact contributed to the anti-tumor effect of IFNγ." (PMID 36812891, 2023). "In this context, the secretion of immunosuppressive molecules such as TGF-β and IDO-1 by tumor cells, and the recruitment of immunosuppressive immune system cells, such as Tregs, into the tumor microenvironment are the lead causes in the creation of an immunosuppressive phenotype." (PMID 37958417, 2023). "Consistently, IDO1 expression was linked to increased metastasis formation in murine tumor models." (PMID 37196768, 2023). "In previous work, it was determined that loss of the BIN1 (bridging integrator 1) tumor suppressor resulted in dysregulated induction of IDO1 in oncogenically transformed skin fibroblasts thereby facilitating immune escape when the cells were grafted into immune competent hosts." (PMID 37182174, 2023). "Our results found that the high expression of IDO1 was observed in tumor tissues and was associated with unfavorable outcomes, indicating that IDO1 may be a potential therapeutic biomarker." (PMID 35760783, 2022). "In view of the marked induction of IDO1 by subtilisin, the experiments were extended to a number of chymotryptic serine proteases related to subtilisin and some of which have been associated with the induction of tumour properties in cells." (PMID 35371018, 2022). "However, the mechanisms underlying the post-translational regulation of IDO1 in tumor cells are incompletely understood." (PMID 36163134, 2022).
tumor (continued). "It is possible that, in cancer types associated with IDO1 up-regulation, the use of IDO1 inhibitors may ‘force’ tumours to up-regulate TDO2: a possibility worthy of investigation." (PMID 36286592, 2022). "IDO1 overexpression and tryptophan deficiency might lead to the dysfunction of effector T cells and tumor immune evasion." (PMID 36483029, 2022). "The reduction in tumor recurrence was also associated with the downregulation of IDO1/TDO2 levels." (PMID 35406118, 2022). "To determine if the observed inhibition in tumor growth by carbidopa is associated with changes in IDO1 expression, we performed RT-qPCR using tumor samples from control and carbidopa-treated mice from both the experiments, i.e. carbidopa in drinking water and carbidopa through oral gavage." (PMID 35997090, 2022). "Ido-1 may represent one of the new potential target for these tumors, since it is not only expressed by cancer cells, but also by tumor associated microenvironment." (PMID 36419183, 2022). "Increased IDO1 activity and increased Trp depletion cause activated T lymphocytes to enter a cell cycle arrest, leading to apoptotic T cell death and promoting immunosuppression of the tumor microenvironment increases and indole production decreases." (PMID 35784338, 2022). "Therefore, upregulation of the IDO1 gene is associated with increased immunosuppression due to T-cell apoptosis and increased metabolites of IDO1 in the tumor microenvironment (TME)." (PMID 36059606, 2022). "Expression of HtrA proteins is associated with tumour initiation and the induction of IDO1 reported here may contribute to these actions, a result which may be linked to the induction of HtrA1 by TGF-β, a prominent inducer of IDO expression." (PMID 35371018, 2022). "Furthermore, IDO1 or IDO2 deficiency can modulate the tumor microenvironment by reducing KTR, enhancing immune cell infiltration and IFN-γ production." (PMID 34422661, 2021). "IDO1 has been shown to be implicated in maternal tolerance towards ‘allogeneic concepti’, in controlling autoimmune diseases and chronic infection, as well as promoting tumor immune escape." (PMID 34943977, 2021). "In addition, the tumor-associated CD163+ macrophages expressed indoleamine-pyrrole 2,3-dioxygenase (IDO1), reaching again 73% in UPSs." (PMID 33478080, 2021). "In conclusion, IDO1’s expression is known to be immunosuppressive and may be involved in tumor immune escape, but it has also been implicated in direct anti-tumor effects." (PMID 34943977, 2021). "Many studies demonstrate that solid tumors may escape immunosurveillance through upregulation of the IDO1 enzyme in cancer cells and tumor microenvironment, a condition associated with poor clinical outcomes." (PMID 33922388, 2021). "Moreover, post-therapy HPD tumors have also displayed transcriptional upregulation of PI3K/AKT and MAPK/ERK pathways, and it has been shown that PI3K and MAPK oncogenic mutations can favor constitutive IDO1 expression on tumor cells." (PMID 33467713, 2021). "Interestingly, elevated IDO1 expression is associated with better outcome in lung adenosquamous carcinoma patients, especially for those after surgical resection of the tumor." (PMID 34422661, 2021). "Hence, exposure to [neratinib + valproate] causes anti-tumor immune responses via multiple overlapping mechanisms; infiltrating NK cells, M1 macrophages and reduced IDO-1 and ODC levels." (PMID 31885880, 2020). "Eicosanoids have been shown to modify the anti-tumor effects of cytotoxic T cells, alter the populations of innate immune cells to favor increases in immunosuppressive cells such as MDSC and tumor associated macrophages, as well as modulating metabolic pathways such as IDO1." (PMID 33364964, 2020). "IDO-1 is an interferon-induced enzyme associated with tumour immunosuppression." (PMID 33153130, 2020). "In vitro neutralizing tumor necrosis factor α (TNFα) could inhibit the tumor progression caused by M2b culture medium and tumor IDO1 expression." (PMID 33214550, 2020).
tumor (continued). "This may be primarily mediated by increased IDO1 expression and subsequent accumulation of Trp metabolites, since IDO1 is either expressed by many tumor cells themselves or by tumor associated cells such as DCs or endothelial cells (ECs)." (PMID 32153576, 2020). "However, the combined inhibition of MERTK and indoleamine-2,3-dioxegenase (IDO1) blocked tumor metastasis and caused tumor regression in 60% of MMTV-Neu mice." (PMID 32346605, 2020). "Of note, the immunosuppressive molecule IDO1, often found in association with tolerogenic DCs35 was predominantly expressed in cDC2s that still retained a clear DC phenotype upon interaction with tumour cells." (PMID 32488012, 2020). "However, Ido1 deficiency altered the immune response in the tumor microenvironment with increased levels of pro-inflammatory cytokines and a reduced number of Treg cells." (PMID 32674255, 2020). "In the tumor microenvironment, tumor cells can induce IDO1 over expression, which causes the depletion of local tryptophan and the accumulation of metabolites such as kynurenine, thereby activating GCN2 and AHR signaling pathways, inhibiting T cell proliferation, and inducing apoptosis." (PMID 33101032, 2020). "In the pre-clinical setting, blockade of PDL1 led to a strong anti-tumor effect and was associated with an intratumoral inflammatory cytokines signature driven by Ifng but also with a modulation of the KP enzymes including Ido1 and Ido2." (PMID 32194552, 2020). "The purpose of this study is to digitally quantify TAM abundance and to characterize TAM immunophenotypes with regard to PD-L1 and IDO-1 expression from diagnostic cHL tumor samples, as well as to associate the findings with clinical characteristics and survival." (PMID 32260340, 2020). "The results showed that high tumour IDO1 intensity was associated with poor survival (p = 0.018)." (PMID 31358801, 2019). "To determine whether the inhibition of tumor growth in H22 HCC-bearing mice caused by H2S was related to IDO1 and immune responses, we examined the expression of IDO1 and CD8+ T cells in tumor tissues." (PMID 30777103, 2019). "The IDO1-expressing humanized MSCs could inhibit the immune response and promote tumor growth in iNOS-deficient mice." (PMID 31149015, 2019). "High number of iNOS+ M1-like macrophages, both in the center of the tumour (CT) and invasive margin (IM), was significantly associated with improved survival (p = 0.009) while high expression of IDO1 or CD47 in the malignant cells was associated with worsened prognosis (p = 0.018, p = 0.046)." (PMID 31358801, 2019). "Furthermore, the altered expression profile of HDACs was also causal in the surviving tumor cells expressing less IDO-1, ODC and PD-L1 and expressing more Class I MHCA." (PMID 29464055, 2018). "In addition, the IDO1 expression level in tumor endothelial cells is associated with the tumor’s response to checkpoint inhibitor treatment in metastatic renal cell carcinoma." (PMID 30068361, 2018). "Moreover, IDO1 is also expressed in antigen presenting cells, which enhances peripheral tolerance to tumor associated antigens (TAAs) in tumor draining lymph nodes." (PMID 29651242, 2018). "Studies into the underlying nature of the IDO1-directed, anti-tumor response are currently ongoing." (PMID 30400835, 2018). "Increased tumor expression of IDO1 has been associated with significantly worse clinical outcomes." (PMID 29921320, 2018). "However, the increased IDO1 in tumour endothelial cells was associated with limitation of the tryptophan influx from the blood circulation." (PMID 29156701, 2017). "While cellular and molecular immunophenotyping demonstrated a robust reprogramming of both innate and adaptive anti-tumor immunity in response to E7046 + E7777 combination therapy, it also induced expression of genes encoding immunosuppressive molecules such as ido1, arg1, PD-1, PD-L1, and Tim3." (PMID 28920002, 2017).